CFAP36 (cilia and flagella associated protein 36)
Description:
May act as an effector for ARL3.
Synonyms: CCDC104; MGC15407; BARTL1
Tractability: PROTAC: ubiquitination databases record sites on it; its protein half-life has been measured.
Gene: Protein-coding gene on chromosome 2 (55,519,559 to 55,545,080, forward strand). Ensembl gene ENSG00000163001.
Subcellular location: Nucleus; Cytoplasm; Cell projection, cilium, flagellum
Subcellular location (Human Protein Atlas): Nucleoplasm; Cytosol; Nuclear bodies; Nucleoli fibrillar center; Primary cilium
Gene Ontology:
Molecular function: protein binding
Cellular component: ciliary transition zone; axoneme; ciliary base; cytoplasm; nucleus; cilium; motile cilium
Genetic constraint (gnomAD): Loss-of-function variants: 12 observed, 22.42 expected, observed/expected ratio (o/e) 0.54, 90% interval 0.34 to 0.87. The upper end of that interval is the gene's LOEUF score, 0.87, which puts it in group 3 of 6, group 1 being the genes least tolerant of losing a copy. Missense variants: 252 observed, 231.02 expected, observed/expected ratio (o/e) 1.09, 90% interval 0.98 to 1.21. Synonymous variants: 70 observed, 72.71 expected, observed/expected ratio (o/e) 0.96, 90% interval 0.79 to 1.17.
Homologues: Orthologues: chimpanzee CFAP36 (99% identical), macaque CFAP36 (97% identical), dog CFAP36 (93% identical), pig CFAP36 (91% identical), mouse Cfap36 (91% identical), rat Cfap36 (90% identical), rabbit CFAP36 (88% identical), guinea pig CFAP36 (87% identical), tropical clawed frog cfap36 (48% identical), zebrafish cfap36 (39% identical), Caenorhabditis elegans cfap-36 (29% identical), Drosophila melanogaster CG14367 (27% identical).
Diseases named in the same sentence as CFAP36 in open-access papers:
CFAP36 is named in the same sentence as 1 disease in open-access papers, as found by Europe PMC text mining. Sharing a sentence is not in itself a finding about the gene and the disease.
CFAP36 shares sentences with these, for which no sentence is quoted: anemia (1 paper).